HLA-G (major histocompatibility complex, class I, G)
Diseases named in the same sentence as HLA-G in open-access papers (continued):
Sharing a sentence is not in itself a finding about the gene and the disease.
breast carcinoma (continued). "We examined the association between HLA-G, its receptor KIR2DL4, mast cells, and breast cancer progression." (PMID 32023940, 2020). "To elucidate the importance of the interaction between KIR2DL4 on mast cells and HLA-G on cancer cells, we co-cultured the HLA-G-positive human breast cancer cell line MCF-7 cells with the human mast cell LAD2." (PMID 32023940, 2020). "Using clinical samples, we have shown that HLA-G-positive breast cancer cells interact directly with KIR2DL4-positive tissue mast cells immunohistochemically." (PMID 32023940, 2020). "In a study of 677 patients with early breast cancer, it has been shown that patients with lost classical HLA-I and expressing HLA-E and HLA-G show a shorter relapse free period, compared to those expressing classical HLA-I." (PMID 32784928, 2020). "Serum HLA-G levels have been determined in high-grade ovarian, colorectal, gastric, esophageal, lung, and breast cancer, melanoma, and neuroblastoma." (PMID 31013867, 2019). "Strikingly, they also found that, breast cancer patients with a high HLA-G protein expression and a low TIL infiltration had a significantly higher risk of recurrence compared to patients with low HLA-G expression and a high TIL density." (PMID 31013867, 2019). "Soluble HLA-G (sHLA-G) levels were significantly increased in plasma in breast cancer patients compared to healthy controls and even correlated with the histological type." (PMID 31013867, 2019). "We examined HLA-G expression in normal mammary and breast cancer cell lines and human normal and breast cancer tissue." (PMID 30400822, 2018). "Expression of HLA-G has been reported in a variety of cancers, including breast cancer, and has been assigned a role in tumor immune escape (Najiet al., 2014;Rouas-Freisset al., 1997;Swetset al., 2016;Zeestratenet al., 2014)." (PMID 29527288, 2017). "To compare HLA-G expression across ICR groups using the breast cancer datasets uploaded to GXB, we start by selecting a dataset." (PMID 29527288, 2017). "The central panel now presents a graphical display of the observed abundance of HLA-G transcripts in breast cancer samples across the different ICR groups, each sample is represented by a single point in a boxplot." (PMID 29527288, 2017). "In fact, they analyzed total sHLA-G and HLA-G levels in extracellular vesicles (EV) in plasma samples from breast cancer (BC) patients, before and after NACT." (PMID 27652273, 2016). "HLA-G was expressed in 18.8% (3/16) of patients with estrogen receptor (ER)-negative breast cancer and 50.9% (29/57) of patients with ER-positive breast cancer." (PMID 24870375, 2014). "Regarding the expression of HLA-G in breast tissue, several studies showed that 41–66% of breast cancer lesions expressed HLA-G." (PMID 24870375, 2014). "HLA-G expression has been identified in several tumors such as breast cancer, glioblastoma, classical Hodgkin's lymphoma, and renal and lung cancers." (PMID 22440091, 2012). "HLA-G abnormal expression has also been suspected of playing a role in various malignancies, including breast cancer." (PMID 18271969, 2008). "HLA-G was highly expressed in the breast cancer cell line McF-7 and its DNA was hypomethylated." (PMID 38427106, 2024). "Progesterone could directly bind to the progesterone response element (PRE) in the HLA-G promoter and induce HLA-G transcription in trophoblast cells, breast cancer cells, and choriocarcinoma cells." (PMID 38310272, 2024). "On the contrary, DNMT inhibitor 5-Aza could induce a rise in HLA-G mRNA and protein in breast cancer cells, which was also confirmed in renal cell carcinoma, melanoma, pancreatic cancer, ovarian cancer, glioblastoma and choriocarcinoma." (PMID 38310272, 2024). "HLA-G protein level was elevated in breast cancer cells in response to estradiol administration." (PMID 38310272, 2024).
breast carcinoma (continued). "The positive correlation of HLA-G expression in tumor lesions with disease stage has been reported for other cancer types including breast cancer, cervical cancer, colorectal cancer, pancreatic carcinoma, renal cell carcinoma, and esophageal squamous cell carcinoma." (PMID 39594832, 2024). "Studies of different pathological conditions have indicated that the HLA-G gene might serve as a clinical marker for the diagnosis or prediction of the clinical outcomes of breast cancer." (PMID 37623251, 2023). "Based on previous studies, whether HLA-G can be used as a marker for clinical diagnosis and treatment of breast cancer patients has also been extensively investigated." (PMID 35185887, 2022). "HLA-G, a non-classical HLA Class I molecule, was highly expressed in breast cancer tissues and associated with tumor progression and poor prognosis of patients." (PMID 35185887, 2022). "HLA-G expression has also been shown to be associated with a shortened time to recurrence, DFS and OS in several other malignancies such as gastric cancer, breast cancer, lung cancer and malignant melanoma." (PMID 35027037, 2022). "A deep understanding of the regulatory role of HLA-G/KIR2DL4 in the immune microenvironment of breast cancer might provide new ideas for the treatment of breast cancer." (PMID 35185887, 2022). "In HER2-positive breast cancer, blocking HLA-G/KIR2DL4 signaling improved trastuzumab resistance." (PMID 36601109, 2022). "Our recent study reported that KIR2DL4, an alternative receptor of HLA-G, might be a novel target in breast cancer immunotherapy." (PMID 35185887, 2022). "A study reported that the expression of HLA-G was associated with both improved relapse-free survival (RFS) and overall survival (OS) of basal-like breast cancer, which might indicate a better status of lymphocyte infiltrating." (PMID 35185887, 2022). "So far, the role of HLA-G/KIR2DL4 in breast cancer immunotherapy has been progressively elucidated." (PMID 35185887, 2022). "MicroRNAs were also found to be involved in the regulation of HLA-G expression in breast cancer." (PMID 35185887, 2022). "All these findings suggest that HLA-G might be an important immune checkpoint in breast cancer immunotherapy." (PMID 35185887, 2022). "We next examined whether the trastuzumab-mediated interplay between HER2-overexpressing breast cancer cells and NK cells regulates HLA-G and KIR2DL4 expression." (PMID 34158475, 2021). "We next generated xenograft breast cancer models using HLA-G-null SK-BR-3 cells." (PMID 34158475, 2021). "Moreover, HLA-G is suggested to be an independent predictor of cancers, such as esophageal squamous cell carcinoma, gastric cancer, breast cancer, and OC." (PMID 34868081, 2021). "Kaplan–Meier analyses did not reveal statistically significant associations between HLA-G expression and clinical outcome of breast carcinoma patients." (PMID 34361031, 2021). "We next probed whether HLA-G on HER2-positive breast cancer cells is involved in the escape from trastuzumab-mediated killing by immune cells." (PMID 34158475, 2021). "A combined study encompassing gene polymorphisms of the HLA-G 3’UTR and exosomal microRNAs could contribute to a better understanding of diagnosis, prognosis, and treatment response in breast cancer." (PMID 35095919, 2021). "Finally, we probed the role of HLA-G/KIR2DL4 in the response of clinical breast cancer to trastuzumab using neoplastic specimens of trastuzumab-resistant and trastuzumab-sensitive patients." (PMID 34158475, 2021). "Increased percentages of HLA-G+CD3+ cells have been observed in the peripheral blood of breast cancer patients, suggesting that these cells may contribute to tumor development by down-modulating antitumor immunity." (PMID 32983083, 2020).
breast carcinoma (continued). "The correlation of unfavorable clinical outcomes with high expression of vesicle-bound soluble HLA-G (sHLA-G) and the presence of stem-cell like CTCs in patients with breast cancer after neo-adjuvant chemotherapy indicates that CTCs exploit sHLA-G to escape NK cell-mediated cytotoxicity." (PMID 32260071, 2020). "For luminal B-like breast cancer samples, an overall low percentage (12–22%) of patients who achieved pCR was observed, independently of the expression of HLA-F and HLA-G isoforms, in comparison with the pCR rates in the HER2+ and triple-negative BC subcohorts (46–86% and 32–71%, respectively)." (PMID 32978482, 2020). "HLA-E and HLA-G overexpression has been shown in HER2+ type of breast cancer." (PMID 32784928, 2020). "We characterized HLA expression in breast cancer and malignant melanoma cell lines and investigated the induction of HLA-G expression by two distinct mechanisms: stimulation with interferon (IFN)-γ or inhibition of methylation by treatment with 5-aza-2’-deoxycytidine (5-aza-dC)." (PMID 32560316, 2020). "In summary, this study suggests that HLA-G and HLA-F may play an immunoregulatory role in breast cancer, on the basis of specific analysis of isoforms and splicing variants." (PMID 32978482, 2020). "Moreover, it has also been reported that a subset of HLA-G+ NK cells possessing suppressive activity are considerably increased in the peripheral blood of breast cancer patients." (PMID 32983083, 2020). "In the present study of HER2+ breast cancer, showing higher pCR rates with high HLA-G1 expression, however, none of the membrane-bound HLA-G isoforms revealed any significant association with pCR." (PMID 32978482, 2020). "Accumulating evidence has shown that HLA-G is highly expressed in a variety of tumour tissues, including breast cancer, cervical cancer, hepatocellular carcinoma (HCC), oesophageal carcinoma (EC), thyroid carcinoma, lung cancer, gastric cancer, colorectal cancer (CRC), and renal cell carcinoma." (PMID 30962267, 2019). "The power of HLA-G +3142G/C genetic variants to predict the metastatic-free survival among breast cancer patients was investigated by comparing patients carrying no risk allele (GG) versus those carrying at least one risk allele (CC and CG)." (PMID 31759373, 2019). "Therefore, we selected the binary manner with the cut-off at 25% of staining area, which distinguish between weakly and moderately stained, and found the relations between HLA-G with breast cancer." (PMID 24870375, 2014). "In the present study, HLA-G was expressed in 43.8% (32/73) of breast cancer tissues." (PMID 24870375, 2014). "HLA-G was observed in 43.8% (32/73) of breast cancer lesions." (PMID 24870375, 2014). "HLA-G expression in breast cancer lesions was also analyzed by immunohistochemistry staining." (PMID 24870375, 2014). "Several studies revealed that HLA-G was more frequently observed in advanced stages of the disease and tumor grade in breast cancer, indicating its considerable clinical relevance to breast cancer." (PMID 24870375, 2014). "In addition, HLA-G expression is up-regulated in tumors and low levels of miR-152 and miR-148a were found in tumors, such as breast cancer and gastrointestinal cancers." (PMID 22438923, 2012). "Recent evidence indicates that HLA-G EVs enhance the immunosuppressive characteristics of ILT-2-negative CD8+ T cells in breast cancer (BC)." (PMID 38562940, 2024). "Furthermore, in breast cancer tissues HLA-G expression was found to be positively correlated with the hormone receptors expression and slightly increased sHLA-G plasma levels were observed in patients with positive hormone receptors compared to those without hormone receptor expression." (PMID 37283737, 2023). "Due to the different immunosuppressive effects of the HLA-G isoforms and the diverse role of HLA-F, these proteins could be of interest for the investigation of pathogenesis and progression and as a therapeutic target for breast cancer." (PMID 32978482, 2020).
breast carcinoma (continued). "There is evidence that HLA-G-bearing EV are an especially crucial factor in immune-tolerance mechanisms operative in malignant diseases, as the total amount of soluble HLA-G has not been associated with disease progression and overall survival in breast cancer patients." (PMID 31382533, 2019). "The expression of HLA-G has been shown in cancer stem cells (CSCs) of certain types of leukemia and renal cancer and in lymph node metastases of thyroid cancer, gastric cancer metastases, metastases of ovarian cancer, malignant melanoma, colon cancer, and breast cancer." (PMID 31013867, 2019). "Of note, high levels of EV and high levels of a EV sub-population expressing the non-classical human leukocyte antigen-G (HLA-G) have been associated with the failure of neoadjuvant chemotherapy and disease-progression in peripheral blood of locally advanced, primary breast cancer patients." (PMID 31382533, 2019). "HLA-G appears to promote tumor progression while Qa-2 acts as a tumor suppressor awaking the immune system to reject tumor cells, as suggested by studies on different cancer cell models, such as melanoma, lymphoma, lung carcinoma, and our own results in mammary carcinoma." (PMID 30574154, 2018). "HLA‐G and/or PD‐L1 expressing cancer cells including NSCLC A549, breast cancer MDA‐MB‐231, ovarian cancer SK‐OV‐3, and hypopharyngeal tumor FaDu cell lines were used." (PMID 39234811, 2024). "In a prior study, we discovered that HLA-G binds to the NK cell receptor KIR2DL4, desensitizing HER2-positive breast cancer cells to trastuzumab." (PMID 37981615, 2024). "Trastuzumab-induced TGF-β and IFN-γ also facilitated HLA-G and PD-L1 expression on HER2-positive breast cancer cells, contributing to trastuzumab resistance." (PMID 38310272, 2024). "In our study, we found that HLA-G desensitizes breast cancer cells to trastuzumab by binding to the NK-cell receptor KIR2DL4 and the blockade of HLA-G/KIR2DL4 axis improves the vulnerability of HER2-positive breast cancer to trastuzumab treatment in vivo." (PMID 36960057, 2023). "Many studies have shown that HLA-G/KIR2DL4 expression in immune microenvironment were correlated with the prognosis and progression of breast cancer." (PMID 35185887, 2022). "HLA-G disrupts ADCC by binding to the NK cell receptor KIR2DL4, making HER2-positive breast cancer cells resistant to trastuzumab." (PMID 36210846, 2022). "HLA-G can desensitize breast cancer cells to trastuzumab by binding to KIR2DL4, an atypical member of the KIR family, which responds to HLA-G via endosomal signaling." (PMID 36601109, 2022). "Then, we reviewed the expression of HLA-G/KIR2DL4 in breast cancer immune microenvironment and the potential of HLA-G/KIR2DL4 application in breast cancer immunotherapy." (PMID 35185887, 2022). "Here, we established that the abundant expression of HLA-G on breast cancer cells and its engagement with the atypical KIR family receptor, KIR2DL4, on NK cells suppress ADCC and contribute to breast cancer resistance to trastuzumab." (PMID 34158475, 2021). "In breast cancer patients receiving neoadjuvant chemotherapy (NACT), the relationship between exosomes carrying HLA-G and the prognosis of the disease has been evaluated." (PMID 34868081, 2021). "The study provides preliminary evidence for the evaluation of HLA-G isoform expression, in particular HLA-G6, as a possible new marker for pCR in HER2+ breast cancer." (PMID 32978482, 2020). "It has been found that in breast cancer and clear cell renal cell carcinoma, macrophages bearing ILT2 and ILT4 receptor, respectively, are present around HLA-G-positive tumor cells, which cooperatively establish an immune-tolerant microenvironment." (PMID 33425752, 2020). "High levels of HLA-G-EVs in breast cancers patients treated with neoadjuvant chemotherapy (NACT) correlates with a bad prognosis, whereas patients with high levels of free soluble HLA-G had better outcome." (PMID 32922387, 2020).
breast carcinoma (continued). "In the present study, we evaluated the extend of HLA class Ia and Ib expression in two breast cancer (MDA-MB-231, MCF-7) and two malignant melanoma (FM-55M2, FM-56) cell lines focusing primarily on HLA-G." (PMID 32560316, 2020). "Coexpression of HLA-G and KIR2DL4 therefore worsens cancer prognosis by mediating cancer invasion and metastatic spread, as has been reported in breast cancer." (PMID 31013867, 2019). "However, the definite mechanism of action of HLA-G in breast cancer remains unknown." (PMID 24870375, 2014). "HLA-G was also widely detected in breast cancer and gastric cancer cell lines independent of HER2 expression." (PMID 34158475, 2021). "Here, we found that the nonclassical histocompatibility antigen HLA-G desensitizes breast cancer cells to trastuzumab by binding to the natural killer (NK) cell receptor KIR2DL4." (PMID 34158475, 2021). "Analysis of 108 HER2-positive patients showed that HLA-G expression correlated with the degree of tumor differentiation and Tumor Node Metastasis staging, but no other characteristics of the breast cancer patients." (PMID 34158475, 2021). "In the present study, however, correlation analyses between isoform-specific HLA-G and HLA-F expression and overall survival were not yet possible, as the study also included patients with recently diagnosed breast cancer." (PMID 32978482, 2020). "This study shows, the HLA-G deregulation can serve as a prognostic marker for patients with ovarian, lung, and gastric cancer but not for breast cancer." (PMID 32867672, 2020). "In contrast, detection of soluble HLA-G in ascites was described to be higher in malignant ascites of ovarian and breast cancer than in ascites of benign disease, but detection of sHLA-G in serum of ovarian cancer patients has not been described." (PMID 24987709, 2014). "Based on its special structure, KIR2DL4 can mediate a complicated cross-talk between immune checkpoint and cytokines in breast cancer microenvironment, and dictate distinct outcome of immunotherapy depending on whether or not HLA-G is engaged." (PMID 35185887, 2022). "We first examined whether HLA-G, a nonclassical histocompatibility antigen involved in immune tolerance, is expressed in breast carcinoma." (PMID 34158475, 2021). "Therefore, our study suggests novel approaches to improving trastuzumab efficacy in HER2-positive breast cancer patients, e.g., antibody- or CRISPR/Cas9-mediated depletion of HLA-G, or development of soluble KIR2DL4 or blockers for the HLA-G/KIR2DL4 interaction." (PMID 34158475, 2021). "This suggests that there could be an interaction between these two classes of HLA molecules and that the presence of HLA-E/HLA-G with or without HLA-I can predict the outcome of relapse free period of breast cancer patients." (PMID 32784928, 2020). "Interestingly, SCC patients with HLA-G expression in combination with downregulation of HLA-A or total classical HLA in the primary tumor had a significantly poorer DSS and DFS, which is in accordance with a study in breast cancer." (PMID 27895918, 2016). "Additionally, it has recently been demonstrated that human leukocyte antigen G (HLA-G) hinders ADCC by binding to the atypical KIR family receptor KIR2DL4 on NK cells, which may help explain why HER2-positive breast cancer is resistant to trastuzumab treatment." (PMID 36210846, 2022). "For example, interactions between NK cell receptor KIR2DL4 and HLA-G have recently been reported to be of importance in human breast cancer, and neither KIR2DL4 nor HLA-G were included in our panels." (PMID 37495775, 2023). "We observed that the HLA-G- or KIR2DL4-neutralizing antibody, but not the ILT2 antibody, significantly increased IFN-γ production by NK cells cocultured with breast cancer cells in the presence of trastuzumab." (PMID 34158475, 2021).